C18orf54 (chromosome 18 open reading frame 54)
Description:
Might play a role in cell proliferation.
Synonyms: LAS2; MGC33382
Tractability: Antibody: UniProt places it where antibodies can reach, with high confidence; UniProt predicts a signal peptide or a membrane-spanning region; its Gene Ontology location is reachable by antibodies, with medium confidence. PROTAC: ubiquitination databases record sites on it.
Gene: Protein-coding gene on chromosome 18 (54,357,903 to 54,385,218, forward strand). Ensembl gene ENSG00000166845.
Subcellular location: Secreted
Subcellular location (Human Protein Atlas): Cytosol; Nucleoplasm; Vesicles; Predicted to be secreted
Gene Ontology:
Molecular function: protein binding
Cellular component: extracellular region
Genetic constraint (gnomAD): Loss-of-function variants: 41 observed, 39.99 expected, observed/expected ratio (o/e) 1.03, 90% interval 0.8 to 1.33. The upper end of that interval is the gene's LOEUF score, 1.33, which puts it in group 5 of 6, group 1 being the genes least tolerant of losing a copy. Missense variants: 608 observed, 576.02 expected, observed/expected ratio (o/e) 1.06, 90% interval 0.99 to 1.13. Synonymous variants: 189 observed, 204.08 expected, observed/expected ratio (o/e) 0.93, 90% interval 0.82 to 1.04.
Homologues: Orthologues: chimpanzee C18H18orf54 (99% identical), macaque C18H18orf54 (94% identical), pig C18orf54 (81% identical), rabbit C18orf54 (76% identical), dog C18orf54 (69% identical), rat C18h18orf54 (67% identical), mouse 4930503L19Rik (65% identical), zebrafish zgc:152948 (22% identical), tropical clawed frog c1h18orf54 (20% identical).